IZUMO1R (IZUMO1 receptor, JUNO)
Description:
Receptor for IZUMO1 present at the cell surface of oocytes (oolemma), which is essential for species-specific gamete recognition and fertilization. The IZUMO1:IZUMO1R/JUNO interaction is a necessary adhesion event between sperm and egg that is required for fertilization but is not sufficient for cell fusion. The ligand-receptor interaction probably does not act as a membrane 'fusogen'. Does not bind folate.
Synonyms: FR-delta; FOLR4; JUNO; Folbp3
Tractability: Antibody: UniProt places it where antibodies can reach, with high confidence; its Gene Ontology location is reachable by antibodies, with high confidence; UniProt predicts a signal peptide or a membrane-spanning region.
Gene: Protein-coding gene on chromosome 11 (94,304,580 to 94,308,146, forward strand). Ensembl gene ENSG00000183560.
Subcellular location: Cell membrane; Cell projection, microvillus membrane
Pathways (Reactome):
Metabolism of proteins: Post-translational modification: synthesis of GPI-anchored proteins
Gene Ontology:
Molecular function: protein binding; signaling receptor activity; folic acid binding; signaling receptor binding
Biological process: fusion of sperm to egg plasma membrane involved in single fertilization; single fertilization; cell adhesion; sperm-egg recognition
Cellular component: plasma membrane; extracellular region; microvillus membrane
Genetic constraint (gnomAD): Loss-of-function variants: 24 observed, 22.89 expected, observed/expected ratio (o/e) 1.05, 90% interval 0.76 to 1.47. The upper end of that interval is the gene's LOEUF score, 1.47, which puts it in group 6 of 6, group 1 being the genes least tolerant of losing a copy. Missense variants: 308 observed, 324.32 expected, observed/expected ratio (o/e) 0.95, 90% interval 0.86 to 1.04. Synonymous variants: 133 observed, 126.67 expected, observed/expected ratio (o/e) 1.05, 90% interval 0.91 to 1.21.
Homologues: Orthologues: chimpanzee IZUMO1R (99% identical), macaque IZUMO1R (96% identical), rabbit IZUMO1R (75% identical), pig IZUMO1R (74% identical), dog IZUMO1R (69% identical), rat Izumo1r (69% identical), guinea pig IZUMO1R (67% identical), mouse Izumo1r (66% identical), zebrafish folr (46% identical), tropical clawed frog folr1 (40% identical). Paralogues in human: FOLR1 (56% identical), FOLR3 (54% identical), FOLR2 (54% identical), RTBDN (16% identical).
Diseases named in the same sentence as IZUMO1R in open-access papers:
IZUMO1R is named in the same sentence as 8 diseases in open-access papers, as found by Europe PMC text mining. Sharing a sentence is not in itself a finding about the gene and the disease. The quoted sentences say what the papers report.
infertile (4 papers, 2020 to 2024). "GPI-anchored protein JUNO (officially named IZUMO1R) was identified as the oocyte receptor of IZUMO1, and Juno KO female mice were also infertile due to impaired sperm–oocyte fusion." (PMID 32295885, 2020).
psoriasis (2 papers, 2024). An autoimmune condition characterized by red, well-delineated plaques with silvery scales that are usually on the extensor surfaces and scalp. "One of the upregulated genes was Izumo1r (upregulated 5.04 fold, P<0.0001), which is expressed in Foxp3+ Treg cells and was recently shown to facilitate Treg tight contacts with γδT cells to mediate psoriasis-like inflammation in the dermis." (PMID 38562928, 2024). "However, this deficiency results in immune dysregulation in the skin, accompanied by the dysregulation of γδT cells, underscoring the importance of Izumo1R expression on Tregs in the development of psoriasis." (PMID 39290699, 2024). "Although the precise role of Tregs in psoriasis requires further exploration, studies using a mouse model with Treg-specific Izumo1r deficiency have shown no significant impact on Treg development and homeostasis." (PMID 39290699, 2024).
female infertility (1 paper, 2023). Diminished or absent ability of a female to achieve conception. "IZUMO1R is implicated in fertilization and barely expressed after fertilization, and Kash5 mutant mice exhibit male and female infertility due to meiotic defects." (PMID 36864840, 2023).
tumor (5 papers, 2014 to 2024). "Izumo1r was barely detectedin the tumor tissue but not in the cultured 4T1 cell line." (PMID 39105761, 2024).
IZUMO1R also shares sentences with these, for which no sentence is quoted: atherosclerosis (1 paper); esophageal squamous cell carcinoma (1); infection (1); male infertility (1).